NTN5 (netrin 5)
Description:
Plays a role in neurogenesis. Prevents motor neuron cell body migration out of the neural tube.
Tractability: Antibody: UniProt places it where antibodies can reach, with medium confidence; UniProt predicts a signal peptide or a membrane-spanning region; its Gene Ontology location is reachable by antibodies, with medium confidence.
Gene: Protein-coding gene on chromosome 19 (48,661,407 to 48,673,081, reverse strand). Ensembl gene ENSG00000142233.
Subcellular location: Secreted
Gene Ontology:
Molecular function: extracellular matrix structural constituent
Biological process: neurogenesis; substrate adhesion-dependent cell spreading
Cellular component: basement membrane; extracellular region
Genetic constraint (gnomAD): Loss-of-function variants: 42 observed, 33.78 expected, observed/expected ratio (o/e) 1.24, 90% interval 0.97 to 1.61. The synonymous counts are far from expectation, so gnomAD's model fits this gene poorly and the ratio says little. Missense variants: 648 observed, 581.29 expected, observed/expected ratio (o/e) 1.11, 90% interval 1.04 to 1.19. Synonymous variants: 325 observed, 242.56 expected, observed/expected ratio (o/e) 1.34, 90% interval 1.22 to 1.47.
Homologues: Orthologues: chimpanzee NTN5 (99% identical), macaque NTN5 (96% identical), dog HSD17B14 (88% identical), pig NTN5 (87% identical), rabbit NTN5 (85% identical), rat Ntn5 (78% identical), guinea pig NTN5 (74% identical), mouse Ntn5 (62% identical), tropical clawed frog ntn5 (47% identical). Paralogues in human: NTN3 (44% identical), NTN1 (43% identical), LAMB4 (30% identical), LAMA5 (29% identical), LAMB2 (28% identical), LAMA2 (27% identical), LAMA3 (27% identical), LAMC3 (27% identical), LAMC1 (27% identical), LAMB1 (26% identical), LAMA1 (25% identical), LAMB3 (25% identical), and 15 more.
Diseases named in the same sentence as NTN5 in open-access papers:
NTN5 is named in the same sentence as 14 diseases in open-access papers, as found by Europe PMC text mining. Sharing a sentence is not in itself a finding about the gene and the disease. The quoted sentences say what the papers report.
Alzheimer disease (1 paper, 2020). A progressive, neurodegenerative disease characterized by loss of function and death of nerve cells in several areas of the brain leading to loss of cognitive function such as memory and language. "NTN5 is primarily expressed in neuroproliferative areas, suggesting a role in adult neurogenesis, which is dysregulated in glioblastoma and Alzheimer’s disease." (PMID 33109261, 2020).
breast carcinoma (1 paper, 2020).
cerebral infarction (1 paper, 2026). An ischemic condition of the brain, producing a persistent focal neurological deficit in the area of distribution of the cerebral arteries. "Adenoviral Netrin-5 delivery in MCAO mice attenuated cerebral infarction, improved functional outcomes, reduced edema, and preserved BBB integrity, evidenced by diminished Evans blue extravasation and albumin leakage." (PMID 41688424, 2026).
colorectal cancer (1 paper, 2016). A primary or metastatic malignant neoplasm that affects the colon or rectum. "The netrin receptor deleted in colorectal cancer (DCC) is a potential receptor for NTN5 in MNs, as similar ectopic neurons were found in Dcc mutant mice, but not in mice deficient for other netrin receptors." (PMID 26858598, 2016).
demyelinating disease (1 paper, 2020). A broad group of disorders that affect the myelin sheaths that cover the neurons. "Of note, the increase in OPCs observed in NTN5 KO mice suggests a potentially new avenue of study toward clinical approaches for demyelinating diseases such as multiple sclerosis." (PMID 33324143, 2020).
inflammatory bowel disease (1 paper, 2025). A spectrum of small and large bowel inflammatory diseases of unknown etiology. "For example, elevated NTN5 transcript level was associated with a shorter parental lifespan, which was mediated by cholesterol, triglycerides, blood pressure, and inflammatory bowel disease." (PMID 40211681, 2025).
tumor (3 papers, 2019 to 2022). "Considering the role of NTN5 in cell migration it is well possible that NTN5 has a role in tumor biology." (PMID 30923634, 2019). "Highly expressed NTN3, NTN5, and NTNG1 are correlated and sensitive to these three drugs, suggesting that the netrin family may be involved in tumor metabolism." (PMID 32251318, 2020).
cancer (2 papers, 2020 to 2025). A tumor composed of atypical neoplastic, often pleomorphic cells that invade other tissues. "The hot spot mutation X342_splice of NTN5 occurred in two cancers (SKCM and UCEC) in two patients, and also encodes a truncated protein." (PMID 32251318, 2020).
NTN5 also shares sentences with these, for which no sentence is quoted: adenocarcinoma (1 paper); Cerebral ischemia (1); glioblastoma (1); ischemic stroke (1); multiple sclerosis (1); papillary renal cell carcinoma (1).